AR (androgen receptor)
Diseases named in the same sentence as AR in open-access papers (continued):
Sharing a sentence is not in itself a finding about the gene and the disease.
prostate carcinoma (continued). "Androgen receptor (AR)+ forkhead box A1 (FOXA1)+ prostate cancer cells are exquisitely sensitive to dual SMARCA2 and SMARCA4 degradation relative to normal and other cancer cell lines." (PMID 34937944, 2022). "IONISAR-2.5Rx is a PS/cET gapmer ASO developed by Ionis Pharmaceuticals and designed to inhibit the expression of the androgen receptor (AR gene) for the treatment of castration-resistant prostate cancer." (PMID 35213992, 2022). "Given the established role of FOXA1 in regulating AR activity in prostate cancer, much interest has been focused on the interplay between FOXA1 mutations and the AR cistrome." (PMID 36212399, 2022). "Almost all prostate cancer cells depend on androgen and AR signals which are closely related to prostate development." (PMID 35594510, 2022). "In prostate cancer cells, androgens can inhibit UGT2B17 expression by activating the androgen receptor, and glucuronidation leads to increased androgen secretion in the body, which will promote prostate cancer progression, forming a vicious cycle." (PMID 36741721, 2022). "Recently, the availability of AR inhibitors used in prostate cancer (PCa) has advanced the possibility to use them in AR positive BC patients." (PMID 36111296, 2022). "Androgen-ablation therapy halts disease progression; however, a significant number of prostate cancer patients develop resistance against AR-antagonists, and this incurable disease is termed castration-resistant prostate cancer (CRPC)." (PMID 35164752, 2022). "The dependence of prostate cancer on androgen receptor (AR) signalling has been extensively exploited; for example, second-generation AR antagonists such as enzalutamide and apalutamide or the androgen synthesis inhibitor abiraterone have been widely used." (PMID 36376335, 2022). "Excluding BET, most of the current research is focused on the PROTAC-based approached on targeting AR, whereas attempts to target other dysregulated transcription factors in prostate cancer via PROTACs is limited." (PMID 35547880, 2022). "TRIM18 has also been implicated in development of prostate cancer, since TRIM18 can bind Androgen Receptor (AR) mRNA to regulate prostate cancer cell proliferation." (PMID 35909127, 2022). "Inhibition of GSK3 and the ensuing inhibition of DNMT1 activity resulted in re-expression of the Androgen Receptor (AR) and Estrogen Receptor (ER) in prostate cancer (PCa) and breast cancer (BCa) cells, respectively." (PMID 35402240, 2022). "The androgen receptor (AR) is a key driver of castration-resistant prostate cancer during the transition from a localized to a metastatic disease." (PMID 36499765, 2022). "Zeta55, a selective inhibitor of HDAC6, was reported to degrade the androgen receptor (AR) and reduce the growth of AR-overexpressing prostate cancer cells both in vitro and in a castration-resistant prostate cancer (CRPC) xenograft model." (PMID 36076996, 2022). "It was also shown that 1, at a concentration of 5 μM, exhibits antiandrogenic activity in human prostate cancer cell lines (e.g., LNCaP), preventing the binding of labeled synthetic androgen R1881 (5 nM) to the androgen receptor (AR)." (PMID 36362320, 2022). "There is an urgent need for exploring new actionable targets other than androgen receptor to improve outcome from lethal castration-resistant prostate cancer." (PMID 36358940, 2022). "It is noted that around 80–90% of prostate cancers are detected as AR-positive (AR+ve) at the time of diagnosis, and AR signaling is crucial for prostate cancer development and progression." (PMID 36499670, 2022). "Our study aimed to address these pressing issues and investigate the incidence and mechanistic foundation for how AR signaling regulates IL1β expression in prostate cancer." (PMID 36561929, 2022). "ADT results in the state of BRCAness, leading to sensitivity of prostate cancer to PARP inhibition in combination with AR signaling inhibitors." (PMID 36010882, 2022).
prostate carcinoma (continued). "Although relationships between the miRNAs and the AR are predominantly studied in relation to prostate cancer and breast cancer, the role of miRNAs and the AR in other diseases has begun to emerge." (PMID 35163477, 2022). "Androgens and the androgen receptor (AR) play key roles during the development of prostate cancer (PCa)." (PMID 35832549, 2022). "AR (Androgen receptor), a ligand-dependent transcription factor, has been shown to involve in prostate cancer." (PMID 35885958, 2022). "The existence of the polyQ expansion in the AR protein also means that SBMA is the sole ligand-dependent polyQ disorder; it shares its causative protein with other diseases including androgen-insensitivity syndrome (AIS) and prostate cancer." (PMID 36187346, 2022). "The resulting gene sets and their associations with patient outcomes reflect, specifically, the key role of AR in shaping the identity of the prostate cancer cell and, more generally, the potential in using the epigenome to create informative gene sets." (PMID 35509021, 2022). "Au‐AR pep‐PROTAC results in suppression of AR levels and induces tumor regression in both enzalutamide sensitive and resistant prostate cancer animal models." (PMID 35971165, 2022). "Their data demonstrated that PROTAC 6 was a promising AR degrader in further extensive evaluations for the treatment of AR + prostate cancer and other human diseases in which AR plays a key role." (PMID 35702041, 2022). "Survival and proliferation of prostate cancer cells depend critically on signaling through the androgen receptor (AR) and, consequently, standard therapies against prostate cancer involve androgen reduction through chemical or surgical castration." (PMID 34986150, 2022). "Intriguingly, long-term overexpression of TR3 for 3 days increased the protein level of AR-V7 significantly more than that of full-length AR in CWR22Rv1 cells as well as in other prostate cancer LNCaP and C4-2 cells." (PMID 35454821, 2022). "Previous study showed that the effect of CysC on modulating the prostate cancer cell invasion was provoked by crosstalk between cystatin C and AR-mediated pathways and Erk2 inhibitor that specifically inhibited MAPK/Erk2 activity." (PMID 36536031, 2022). "Because androgen receptor (AR) signaling promotes growth and survival of prostate cancer (PC), blocking AR activation has been the cornerstone of treatment for more than 70 years." (PMID 36453547, 2022). "To date, efforts to target AR pre-mRNA in prostate cancer have been dominated by antisense oligonucleotide strategies that appear promising but have yielded very limited clinical success." (PMID 35087237, 2022). "In prostate cancer, quercetin inhibits the expression of androgen receptor (AR) and AR-mediated PSA expression at the transcriptional level with the inhibition of tumor progression." (PMID 36235389, 2022). "Prostate cancer with neuroendocrine differentiation was usually considered as AR-null with resistance to the AR-directed interventions." (PMID 36033483, 2022). "KIF20A, a kinesin, promotes the progression of castration-resistant prostate cancer through autocrine activation of the androgen receptor." (PMID 36531013, 2022). "This study demonstrated the possibility of developing an orally active AR degrader for the treatment of prostate cancer." (PMID 35680848, 2022). "AR-prostate cancer has a poor prognosis, with the majority of patients dying within two years and no clinically approved targeted treatment options." (PMID 35453603, 2022). "Enzalutamide is a small molecule compound targeting the androgen receptor and it is used to treat prostate cancer." (PMID 35768871, 2022).
prostate carcinoma (continued). "In the last decades, several efforts are been made to identify new biomarkers with a predictive and/or prognostic role, and the most relevant pathway explored in prostatic cancer depends on AR." (PMID 35565349, 2022). "Androgen promotes prostate cancer (CaP) growth by binding to the androgen receptor expressed on both normal and cancerous prostate cancer cells." (PMID 36033455, 2022). "This is, however, altered in prostate cancer, where the AR elicits an aberrant gene expression program due to gain or loss of binding sites and to reactivation of developmental epigenetic processes, ultimately leading to uncontrolled tumor proliferation." (PMID 36611998, 2022). "In prostate cancer, TXNDC5 can directly interact with and stabilize the AR protein to promote Castration-resistant prostate cancer development and growth." (PMID 35296659, 2022). "The goal of the present study was to define the signaling pathways regulated by metformin in androgen-receptor (AR) positive, castration-resistant prostate cancers." (PMID 36175875, 2022). "EP1-001 has been reported to be efficacious in the treatment of prostate cancer, where AR is thought to play an increasingly important role in tumor progression." (PMID 36555703, 2022). "Accordingly, SOD mimetics were proposed with therapeutic effects on prostate cancer cells by reducing oxidative stress and suppressing AR expression." (PMID 36551308, 2022). "Our results suggest that SPA/BAT can significantly downregulate MYC expression, and this occurs only in prostate cancer with high AR activity." (PMID 36194476, 2022). "Overall, these data uncover chronological modification events in AR that allows prostate cancer to evolve through progressive stages to reach the resilient recurrent CRPC stage, opening up a therapeutic vulnerability." (PMID 35704598, 2022). "Androgen receptor (AR) plays an important role in the progression of prostate cancer and has been targeted by castration or AR-antagonists." (PMID 36335093, 2022). "Here, we provide the first comparison between AR-NTD inhibitors and AR-LBD inhibitors on androgen-regulated gene expression in prostate cancer cells using cDNA arrays, GSEA, and RT-PCR." (PMID 35053548, 2022). "Inhibition of NF-kB signaling resensitizes castrate-resistant prostate cancer cells to androgen receptor targeted therapies." (PMID 36551557, 2022). "Notch signaling has been reported to become activated in prostate cancer cell lines exhibiting resistance to the clinically available AR inhibitor enzalutamide, as verified by the increased levels of cleaved NOTCH1, HES1 and c-MYC." (PMID 35954292, 2022). "It is conceivable that eliminating the AR protein in prostate cancer cells is a promising solution to provide a potential curative outcome." (PMID 35372068, 2022). "In prostate cancer, the PCR2-LncRNA HOTAIR association represses the androgen receptor transcription by complexing to its 5′-flanking promoter region and enhancing prostate cancer stem/progenitor cells and invasion." (PMID 36359888, 2022). "Dihydrotestosterone causes acetylation of the androgen receptor (AR), and HDACi increase p300 binding while reducing N-CoR/HDAC/Smad3 co-repressor binding, improving cell survival and growth in prostate cancer cells both in vivo and in vitro." (PMID 36034650, 2022). "Neuroendocrine differentiation gives rise to a more aggressive and malignant clinical phenotype, which has a higher incidence under the exposure to AR-directed therapies in prostate cancer patients." (PMID 36159187, 2022). "In AR-positive prostate cancer cells, OCT4 forms LLPS with the AR and pioneer transcription factor FOXA1." (PMID 35966880, 2022). "As an endocrine-dependent malignancy, the AR pathway is necessary for the development and progression of prostate carcinoma, and the coactivators of AR have been characterized as key regulators of AR activation." (PMID 35444697, 2022).
prostate carcinoma (continued). "USP14 is elevated in prostate cancer and AR-positive BCa, and the expression of USP14 is positively correlated with that of AR." (PMID 36423684, 2022). "Another study in prostate cancer (PCa) cells has shown that ING1b silencing suppresses the androgen receptor (AR)-mediated transactivation of AR targets, resulting in a reduction in the growth of these cells." (PMID 35804879, 2022). "Disrupting the interaction between SRC1/2 and the AR inhibits AR activity in castration-resistant prostate cancer cells." (PMID 36551557, 2022). "In Prostate cancer the androgen receptor (AR) plays a significant role in the development, maintenance and progression of prostate cancer." (PMID 35326427, 2022). "PROTAC 8 exhibited excellent selective cytotoxicity in the BET inhibitors sensitive cancer cell lines, including AR-positive prostate cancer cell lines." (PMID 35702740, 2022). "Androgen deprivation therapy, which aims to inhibit AR production and AR signaling, still functions as the mainstay in the treatment of early-stage prostate cancer." (PMID 36033483, 2022). "Further, new fascinating aspects concerning the intersection of the androgen receptor with survival factors as well as calcium channels have been reported in cultured prostate cancer cells and mouse models." (PMID 35222290, 2022). "For example, in prostate cancer cells, androgen-receptor mediated signaling promotes the uptake of fatty acids from the extracellular environment while PI3K / Akt signaling drives de novo fatty acid synthesis." (PMID 35148308, 2022). "While the status quo, as it pertains to treatment of advanced prostate cancer, is persistent and potent AR inhibition, this work provides rationale to alternate between AR inhibition and activation with BAT to prolong the lives of patients with this disease." (PMID 36194476, 2022). "The growth of prostate cancer is dependent on the androgen receptor (AR), which serves as a ligand‐specific transcription factor." (PMID 34057812, 2022). "BRD4 overexpression degrades AR and deregulates its expression, leading to prostate cancer or castration-resistant prostate development." (PMID 35401196, 2022). "In summary, metformin regulates activation of the AR signaling pathway as well as other pathways critical for the growth and survival of human prostate cancer cells." (PMID 36175875, 2022). "Perturbation of p300/CBP function decreases AR activity and reduces tumor cell growth in prostate cancer models." (PMID 36551557, 2022). "This has led to the use of androgen-deprivation therapy (ADT)/AR-signaling inhibitors (ARSi) as a standard treatment regimen for prostate cancer, which is often administered in combination with chemotherapy, radiotherapy and/or immunotherapy." (PMID 36671452, 2022). "The mutation-driven transformation of clinical anti-androgen drugs into agonists of the human androgen receptor (AR) represents a major challenge for the treatment of prostate cancer patients." (PMID 36139361, 2022). "Both EPPI and CPPI at 25 μM inhibited AR nuclear localization in prostate cancer cells, which was reversed when the androgen level (R1881) was over 1.0 nM level, a physiological androgen concentration." (PMID 35372068, 2022). "Co-inhibition of androgen and Wnt-signaling pathways significantly represses the growth of AR-positive tumor cells in both ex-vivo and in-vivo, implicating co-targeting therapeutic strategies for these pathways to treat advanced prostate cancer." (PMID 35902588, 2022). "GATA2 has been shown to be an important transcription factor together with androgen receptor (AR) in prostate cancer cells." (PMID 35203681, 2022). "The acquisition of forkhead transcription factor FOXC2 by AR+ prostate cancer cells led to NED and resistance to enzalutamide and docetaxel." (PMID 35447888, 2022). "Subsequently, OCM was added to prostate cancer cells to investigate its potential effect on prostate cancer cell proliferation and androgen receptor (AR) activation status." (PMID 36140255, 2022).
prostate carcinoma (continued). "SPINK1, which is highly expressed in prostate cancer, is transcriptionally inhibited by AR and its corepressor, REST, while AR antagonists alleviate this inhibition and lead to upregulation of SPINK1." (PMID 35223512, 2022). "They enhance the activation of ligand-dependent and ligand-independent AR-mediated genes and promote the proliferation of prostate cancer cells." (PMID 35103065, 2022). "Lipid accumulation in prostate cancer cells accelerates androgen synthesis, which can promote AR reactivation and/or abnormal activation, leading to CRPC phenotype." (PMID 35053570, 2022). "The most frequently used keywords were “androgen receptor” (n = 1,209), “breast-cancer” (n = 690), “expression” (n = 545), “breast cancer” (n = 410), “prostate-cancer” (n = 290), and so on." (PMID 35800434, 2022). "For example, the presence of FGF7-positive CAFs isolated from prostate cancer biopsies is linked to localized prostate cancer, whereas MMP-11, AR and HSPA1α positively correlate with metastatic CRPC, established by QRTPCR and IHC." (PMID 36671452, 2022). "As a transcription factor, FOXA1 can bind to androgen receptor (AR) and is highly expressed at the early stage of prostate cancer." (PMID 35968505, 2022). "Prostate cancer progression depends on androgens, therefore, reducing androgen levels or blocking the androgen receptor (AR) can inhibit prostate cancer." (PMID 37113653, 2022). "GR appears to be a key regulator of advanced prostate cancers, for GR expression is elevated in metastatic prostate cancers, particularly those that have developed resistance to drugs that target the AR signaling pathway." (PMID 36175875, 2022). "Androgens are the circulating hormone activators of the AR and therefore drive prostate cancer growth and progression in mCRPC patients as well as laboratory prostate cancer cell models." (PMID 37435458, 2022). "Signal Transducer and Activator of Transcription 3 (STAT3) is known to be involved in castration-resistant prostate cancer and to interact with androgen receptor (AR)-signaling." (PMID 35917644, 2022). "Prostate cancer is one of the leading lethal malignancies in males, and androgen receptor (AR), a ligand-dependent transcription factor, plays a pivotal role in the development, progression, and metastasis of prostate cancers." (PMID 35454821, 2022). "Accordingly, the attenuation of KDM5D expression led to increases in H3H4me3 marks in promoter regions of AR-regulated genes as well as protection against docetaxel in AR-positive prostate cancer cell lines." (PMID 35884386, 2022). "Taken together, these findings indicate that SIRT7 expression promotes the proliferation, metastasis, and androgen-induced autophagy of prostate cancer via induction of AR signaling." (PMID 36291902, 2022). "Specifically, we will discuss the impact of key prostate cancer regulators, as well as the role of epigenetic and chromatin regulators in relation to the AR cistrome and the transformation of normal prostate epithelium." (PMID 36212399, 2022). "FOXA1 helps to shape AR signaling through direct interactions with the AR and drives the growth and survival of normal prostate and prostate cancer cells." (PMID 35627227, 2022). "The Androgen receptor (AR) is the receptor protein mediating the androgen action and essential for prostate cancer development." (PMID 35966880, 2022). "Under high concentration (over 500 nM), Au‐AR pep PROTAC show totally inhibition of the growth of AR‐positive prostate cancer cells." (PMID 35971165, 2022). "In prostate cancer, infiltrating MCs can reduce androgen receptor (AR) transcription and increase the aggressiveness of prostate cancer cells by increasing MMP9 expression." (PMID 36591235, 2022). "While the function of AR in prostate cancer is better recognized, the significance of AR signaling in BC is currently the subject of growing research." (PMID 36548336, 2022).